BECN1 (beclin 1)
Diseases named in the same sentence as BECN1 in open-access papers (continued):
Sharing a sentence is not in itself a finding about the gene and the disease.
ovarian carcinoma (continued). "Previous studies using IHC and a Western blot have demonstrated elevated Beclin 1 and LC3 expression in advanced ovarian cancer tissue samples, whereas our study utilized ELISA on ascitic fluid." (PMID 40125128, 2025). "Beclin‐1, the mammalian homolog of ATG6, has been reported to undergo monoallelic deletion in human breast and ovarian cancers, supporting its role as a tumor suppressor." (PMID 40883962, 2025). "Icariin induces the emergence of autophagosomes and modulates autophagy-related proteins (e.g., p62, Beclin-1, LC3-I, and LC3-II) in breast cancer (MDA-MB-468 and 4T1), cervical cancer (Hela) and ovarian cancer (SKVCR) cells." (PMID 40490812, 2025). "Moreover, the absence of the autophagy-associated gene Beclin-1 (BECN1), which plays a crucial role in phagophore formation, is noted to show decreased autophagy and increased cell proliferation in various types of human breast, prostate, and ovarian cancers." (PMID 39201332, 2024). "LTX-315, a polypeptide, controls the Beclin-1/PI3K/mTOR axis to adjust autophagy and drug responsiveness in ovarian cancer." (PMID 39650649, 2024). "Silencing the expression of ATG7 or BECN1, two autophagy genes, rescued the migratory phenotype of the NKX3-2-silenced ovarian cancer cells." (PMID 39513923, 2024). "Important evidence for the role of autophagy in tumor suppression comes from the depletion of the essential autophagy regulator BECN1 (Beclin 1, also known as autophagy-related gene 6 (ATG6)) in human breast, prostate, and ovarian cancers." (PMID 36875752, 2023). "Emblica officinalis extract reduces cell proliferation in ovarian cancer OVCAR3 cells, dose- and time-dependently, by significantly increasing the expression of the autophagy proteins BECN1 and LC3B-II in vitro." (PMID 36497321, 2022). "In summary, the present study demonstrates that the concurrent low expression of BECN1 and BRCA1 is sufficient to make ovarian cancer cells more sensitive to chemotherapeutics." (PMID 33670664, 2021). "Our analysis demonstrates that the concurrent low expression of BECN1 and BRCA1 is sufficient to make ovarian cancer cells more sensitive to chemotherapeutics." (PMID 33670664, 2021). "Under the same conditions, autophagosome proteins such as BECN1, p-ULK1, ATG5, and LC3B were induced by β-sitosterol in the examined ovarian cancer cells." (PMID 34679718, 2021). "Our findings demonstrated that ING5 up-regulated LC-3B, Beclin 1 and ATG13 expression with autophagy strengthened in ovarian cancer cells, indicating that ING5 induced autophagy in Beclin 1-dependent manner." (PMID 29262575, 2017). "Study also suggested that low level of Beclin-1 and PTEN resulted in drug resistance through reducing autophagic activity in the epithelial ovarian cancer tissues." (PMID 27825125, 2016). "In the present study, the protein expression of Beclin-1 and PTEN in ovarian cancer tissues was detected using immunohistochemistry." (PMID 25789037, 2015). "Metformin is used in diabetes mellitus; it is thought to trigger AMPK upstream of the Becn1/Ulk1/Vps34 complex, though it has additional metabolic effects that may impact stem cells and contribute to its documented capacity to improve survival of ovarian cancer patients." (PMID 26418751, 2015). "The expression of the Beclin-1 and PTEN proteins, in drug-resistant and drug-sensitive ovarian cancers, was detected using immunohistochemistry and analyzed for potential correlations." (PMID 25789037, 2015). "The results suggested that Beclin-1 and PTEN protein expression decreased in the drug-resistant ovarian cancer tissues." (PMID 25789037, 2015).
ovarian carcinoma (continued). "BECLIN 1 was initially isolated as an interactor of the oncogenic antiapoptotic protein BCL-2, and it was reported to be deleted in up to 75% of human ovarian cancers." (PMID 25136588, 2014). "Whether Beclin 1 expression is associated with the prognosis of ovarian cancer is not yet clear." (PMID 24675697, 2014). "In this same line, a decreased level of BECLIN 1 expression, especially in conjunction with increased expression of BCL-xL, was correlated with poor prognosis in ovarian cancer bearing patients." (PMID 25136588, 2014). "In this work, we assessed by immunohistochemistry and immunofluorescence the expression of BECLIN 1 and of LC3 in various histologic subtypes of ovarian cancer." (PMID 25136588, 2014). "Thus, we speculated that defect in Bcl-xL expression may influence the Beclin 1-related prognosis in ovarian carcinoma, and that coordination of autophagy and apoptosis may play a more significant role in the tumorigenesis and/or progression of this human malignancy." (PMID 23573264, 2013). "The absence of critical autophagy regulators, such as Beclin-1 (ATG6) and ATG5, has been linked to heightened vulnerability to tumorigenesis in multiple malignancies, including breast and ovarian cancers." (PMID 40710325, 2025). "Silencing TUG1 decreased Beclin-1 and the conversion of LC3B-I to LC3B-II in ovarian cancer cells." (PMID 36899946, 2023). "Monoallelic co-deletion of BECN1 and BRCA1 has been reported in 40-75% of sporadic ovarian cancers." (PMID 33670664, 2021). "While co-deletion of BECN1 with the well-established tumor suppressor BRCA1 occurs in the vast majority of BRCA1 deletion CNAs, BECN1 has not been directly tested as a tumor suppressor in the context of ovarian cancer." (PMID 31923184, 2020). "Similarly, ellagic acid (36.6 μM) inhibited cell growth and the invasiveness of ovarian cancer SKOV-3 cells and stimulated apoptosis by activating cytotoxic autophagy, as indicated by the increase in the levels of Beclin 1, ATG5, LC3I/II and decrease in p62." (PMID 32927836, 2020). "In conclusion, a reduction in autophagic activity, induced by the interaction between Beclin-1 and PTEN, may lead to drug resistance in cases of ovarian cancer." (PMID 25789037, 2015). "Thus, to improve the chance to cure ovarian carcinomas, one should carefully consider whether to employ autophagy inhibitors or autophagy-enhancer drugs in the chemotherapy cocktail depending on the ratio of BECLIN 1 and BCL-2 expression and the actual level of autophagy in the cancer cells." (PMID 25136588, 2014). "We used immunoblotting to compare the overexpression of Beclin 1 in ovarian carcinomas at the protein level with that in normal ovarian tissues." (PMID 24675697, 2014). "Nevertheless, the prognostic significance of Beclin 1 in ovarian carcinoma and its relationship with Bcl-xL expression have not been elucidated." (PMID 23573264, 2013). "Induction of AMPK, ATG12, beclin-1 and/or cleavage of LC3 occurred at physiologically attainable L-ASP concentrations (0.3–1 U/ml) in two ovarian cancer cell lines and the primary culture HMVEC cells; similar beclin induction results were observed in CAOV3 cells as well." (PMID 22333033, 2012). "Therefore, Beclin-1 appears non-essential for autophagy induction in ovarian cancer in vitro cultures." (PMID 26239434, 2015). "Therefore, Beclin-1 may interact with PTEN to participate in the mechanism of drug resistance and the changes in macrophage activity observed in cases of drug-resistant ovarian cancer." (PMID 25789037, 2015).
ovarian carcinoma (continued). "Indeed, deletions encompassing both genes (BRCA1 and beclin-1) and deletions of only BRCA1 but not beclin-1 were found in breast and ovarian cancers, which is consistent with BRCA1 loss representing the primary driver mutation in these cancers." (PMID 25328887, 2014).
hepatocellular carcinoma (129 papers, 2010 to 2025). A malignant tumor that arises from hepatocytes. "Mouse models with BECN1 allelic loss show an increased susceptibility to spontaneous lung adenocarcinoma, lymphoma, and liver carcinoma." (PMID 36760166, 2023). "Becn1+/− mice show an increased incidence of spontaneous tumors, including B cell lymphomas, lymphoblast cell lymphoma, hepatocellular carcinomas, and lung adenocarcinoma, while Becn1−/− cause the embryonic lethality." (PMID 36230664, 2022). "High expression of BECLIN 1 along with low expression of BCL-2 associates with good prognosis in non-Hodgkin lymphomas and, conversely, low expression of BECLIN 1 with high expression of BCL-xL associated with poor prognosis in hepatocellular carcinomas." (PMID 33670664, 2021). "In contrast to Becn1+/+ mice, Becn1+/− mice had a higher risk of lung cancer, hepatocellular carcinoma, and lymphoma." (PMID 32098126, 2020). "Higher Beclin 1 level has been reported to be associated with better prognosis in patients with hepatocellular carcinoma, high-grade gliomas, non-Hodgkin's lymphomas or gastric cancer." (PMID 28881721, 2017). "Allelic loss of Beclin 1 gene rendered partially autophagy defection and induced spontaneous hepatocellular carcinoma in mice." (PMID 24303007, 2013). "On the other hand, beclin-1-deficient mice suffer from a high incidence of spontaneous tumors such as lymphoma, lung adenocarcinoma, and hepatocellular carcinoma." (PMID 24122254, 2013). "In patients with hepatocellular carcinoma and gastric cancers, reduced Beclin-1 expression is associated with a poor prognosis, while high expression is associated with favourable prognosis for salivary carcinoma and lymphoma patients." (PMID 23765161, 2013). "The loss of beclin-1 expression was correlated with poor prognosis in colonic carcinomas, lymphomas and hepatocellular cancers." (PMID 23935917, 2013). "Beclin-1 deficient mice developed lymphoma, lung carcinoma, and liver carcinoma." (PMID 37736508, 2023). "NO induces apoptosis and inhibits autophagy in human hepatoma cells by disrupting the Beclin 1/VPS34 association and increasing the Bcl-2/Beclin 1 interaction, which may provide a novel strategy for the treatment of hepatocellular carcinoma (HCC)." (PMID 34768858, 2021). "A clinical study indicated that the reduced expression of BECN1 is associated with hepatocellular carcinoma (HCC) grade, suggesting its potential as a prognostic biomarker for HCC." (PMID 40723786, 2025). "Furthermore, Beclin-1 down-regulation linked to autophagy defect may be associated with malignant phenotype and poor prognosis of hepatocellular carcinoma." (PMID 23935917, 2013). "Autophagy induction has been observed in hepatoma cells (Hep3B) treated with regorafenib, marked by an increase in both Beclin 1 and LC3-II and a decrease in Bcl-2 levels." (PMID 39272847, 2024). "Another element that controls autophagy in liver cancer is Oroxylin A. Oroxylin A was utilized to trigger Beclin 1-facilitated macroautophagy in the HepG2 cell line of human hepatocellular carcinoma." (PMID 39650649, 2024). "Deletion of ATG5 results in a tumor-suppressive phenotype, similar to abnormal BECN1 in cancer models, but only benign hepatomas in a mouse liver model." (PMID 36831455, 2023). "Amygdalin has been demonstrated to stimulate the apoptotic process by upregulating caspase-3 expression and downregulating Bcl-2 expression, as well as inhibiting HepG2 and EAC hepatocellular cancer cell proliferation and upregulating Beclin-1 expression." (PMID 37762572, 2023). "Mouse studies have confirmed the tumor suppressor role of Beclin 1 as heterozygous knockout of Beclin 1 leads to higher rate of spontaneous malignancies such as lymphomas and lung or hepatocellular carcinomas." (PMID 37598181, 2023). "Downregulation of ASPP2 also confers resistance to apoptosis induced by 5-FU- and etoposide by promoting BECN1-dependent autophagy in hepatocellular carcinoma cells." (PMID 37547633, 2023).
hepatocellular carcinoma (continued). "Beclin-1 is one of the key proteins of autophagy progress Research has shown that sorafenib and its derivative sc-59 induce hepatoma autophagy through the SHP-1/STAT3/MCL-1/Beclin-1 pathway." (PMID 37181755, 2023). "For instance, TGF-β activates autophagy in human hepatocellular carcinoma cells by upregulating the levels of Beclin 1, Atg5 and Atg7." (PMID 36230955, 2022). "The point of CHOP crosstalk has been found to induce the nuclear translocation of Bcl-2 to release beclin-1 and induce autophagic apoptosis in hepatocellular carcinoma cells." (PMID 35815056, 2022). "Monoallelic deletion of Beclin 1, a tumor suppressor, is observed in hepatocellular carcinoma, ovarian and breast cancer." (PMID 34071600, 2021). "Reduced expression of Beclin 1 in tumor tissues was observed in 44 patients with hepatocellular carcinoma." (PMID 34071600, 2021). "Our results showed that the expression of p62 was decreased, and the expression of Beclin-1 was increased after MHCC-97L hepatoma cells were treated with the combination of radiation and SSd." (PMID 33628104, 2021). "To summarize, in this study, the expression of BCL2L10 and BECN1 in hepatoma cells and their effects on the autophagy of hepatoma cells was observed." (PMID 30696802, 2019). "Ovothiol A, from Paracentrotus lividus oocytes, induced the formation of autophagic vacuoles and expression of specific autophagic molecular markers, LC3B-I, LC3B-I to LC3B-II conversion, and BECN1 in human liver carcinoma Hep-G2 cells." (PMID 27537898, 2016). "Decreased Beclin 1 expression has been correlated with a lower survival rate in patients with esophageal cancer, hepatocellular cancer and glioblastoma." (PMID 27683118, 2016). "Compared with corresponding normal tissues, Beclin-1 expression was reported to be low in hepatocellular carcinoma and colorectal cancer." (PMID 28070138, 2016). "We interpreted these results as an inhibition of autophagic proteins by alcohol similar to conclusions of others who found that ethanol lowered LC3-II and Beclin-1 levels in hepatocytes and HepG2 cells or in immune cells or in a rat hepatoma cell line." (PMID 26501338, 2015). "Findings of a recent study showed that berberine extracts promoted autophagy by activating beclin 1 expression and activated caspase-9 to induce apoptosis in hepatoma cells." (PMID 24676394, 2014). "Reduced Beclin 1 expression in hepatocellular cancer is often accompanied by the increased expression of antiapoptotic Bcl-XL, increasing the survival of hepatocellular cancer cells." (PMID 24675697, 2014). "Yue reported that BECN1+/− nude mice showed reduced autophagic activity and an increased incidence of spontaneous tumors, including lymphoma, hepatocellular carcinoma and lung adenocarcinoma." (PMID 24675697, 2014). "The HBV X protein sensitizes hepatoma cells to starvation-induced autophagy via the upregulation of Beclin-1 expression." (PMID 24765136, 2014). "Recent studies have revealed that the expression of Beclin-1 is decreased in various human cancer types, such as breast, cervical, esophageal, lung cancers, hepatocellular carcinoma, and cutaneous melanoma." (PMID 23578251, 2013). "Loss of Beclin-1 was linked to poorer survival rate in stage III colon cancer, esophageal squamous cell carcinoma, hepatocellular carcinoma, intrahepatic cholangiocarcinoma, pancreatic ductal adenocarcinoma, chondrosarcoma, and several types of lymphoma." (PMID 23578251, 2013). "Our study was designed to determine autophagic flux in matrine-treated hepatoma cells and revealed the association of matrine-induced autophagy with PI3K/AKT/mTOR pathway and beclin-1." (PMID 24287900, 2013). "As a result of this study, it was suggested that serum Beclin-1 and ATG-5 could serve as novel biomarkers for predicting the risk of hepatocellular carcinoma." (PMID 40430125, 2025).
hepatocellular carcinoma (continued). "Furthermore, several studies have reported decreased levels of Beclin-1 in various types of cancer, including cervical squamous cell carcinomas and hepatocellular carcinomas." (PMID 40248706, 2025). "It has been demonstrated that hypoxia-induced autophagy may serve as a protective mechanism against apoptosis in hepatocellular carcinoma cells during periods of nutritional restriction, potentially through a Beclin-1-dependent pathway." (PMID 40248706, 2025). "HYSA induced autophagy in hepatocellular carcinoma cells by promoting Beclin 1 expression and inhibiting ERK phosphorylation, indicating HYSA may be a potential therapeutic agent for hepatocellular carcinoma." (PMID 38799156, 2024). "Mice with heterozygotic BECN1 develop lymphoma, hepatocellular carcinoma, and lung adenocarcinomas." (PMID 36831455, 2023). "For example, SPHK1, a regulator of sphingolipid metabolism, by binding TRAF2 (TNF receptor-associated factor 2) and Beclin-1, activates autophagy and thereby induces the degradation of E-cadherin, EMT, and the metastatic progression of hepatocellular carcinoma." (PMID 34944948, 2021). "Similarly, the histone deacetylases SIRT1 and SIRT6 promote the metastatic potential of melanoma and hepatocellular carcinoma cells, respectively, by deacetylating Beclin-1 and accelerating autophagic degradation of E-cadherin." (PMID 34944948, 2021). "Furthermore, a reduced expression of autophagy genes (ATG5, ATG7 and Beclin-1) has been observed in hepatocellular carcinoma (HCC) cells." (PMID 33743781, 2021). "Based on the findings to date, we hypothesized that LETM1 regulates autophagy and apoptosis through activation of AMPK-mediated Beclin-1/Bcl-2 complex dissociation in hepatocellular carcinoma." (PMID 33552978, 2020). "Immunofluorescence assay showed that BCL2L10 and Beclin 1 were co-located in hepatoma cells." (PMID 30696802, 2019). "BCL2L10 had a low expression in HCC tissues and cells, which could combine with BECN1 to induce autophagy of hepatoma cells." (PMID 30696802, 2019). "In hepatomas cells, sphingosine kinase 1 (SPHK1) could induce EMT and promote cell invasion by enhancing the K63-linked ubiquitination of BECN1, thus accelerating CDH1/E-cadherin lysosomal degradation." (PMID 31272261, 2019). "However, previous studies have obtained contradicting results regarding the clinical and prognostic value of Beclin-1 in hepatocellular carcinoma (HCC)." (PMID 30107804, 2018). "Furthermore, ASPP2 can induce the expression of damage-regulated autophagy modulator (DRAM) that cooperates with free Beclin-1 to induce autophagic or apoptosis in hepatoma cells." (PMID 28392757, 2017). "However, other studies have reported that high Beclin-1 expression was related to good prognosis in patients with tumors such as intrahepatic cholangiocarcinoma, colorectal cancer, and hepatocellular carcinoma." (PMID 28070138, 2016). "For example, apoptotic death of hepatoma cells expressing the oncogenic HBV X protein increases when autophagy is blocked, and the infection with Japanese encephalitis virus increases caspase activation and cell death in beclin-1 or Atg5-deficient cells." (PMID 24490870, 2014). "In hepatocellular carcinoma, Beclin 1 inactivation related autophagy defection was correlated with malignant clinicopathological features, and positive Beclin 1 expression predicted a better overall survival and disease-free survival in a Bcl-X(L)-positive expression backgroun.." (PMID 24303007, 2013). "Studies in mice have demonstrated that monoallelic deletion of beclin-1 increases the frequency of spontaneous malignancies including hepatocellular carcinoma, B cell lymphoma and lung adenocarcinomas in beclin-1 +/- mice, suggesting beclin-1 as a haploinsufficent tumor suppressor gene." (PMID 21299897, 2011).